MIR1302-2HG (MIR1302-2 host gene)
Gene: Long non-coding RNA gene on chromosome 1 (28,589 to 31,109, forward strand). Ensembl gene ENSG00000243485.
Gene Ontology:
Biological process: miRNA-mediated post-transcriptional gene silencing